CDKN1A (cyclin dependent kinase inhibitor 1A)
Diseases named in the same sentence as CDKN1A in open-access papers (continued):
Sharing a sentence is not in itself a finding about the gene and the disease.
lung carcinoma (continued). "Taken together, these results demonstrated that EHMT1 knockdown increased CDKN1A expression in lung cancer cell lines and that upregulation of CDKN1A expression induced cell cycle arrest and apoptosis." (PMID 34214254, 2021). "Knockdown of EHMT1 in lung cancer cell lines upregulated CDKN1A expression and induced both apoptosis and cell cycle arrest." (PMID 34214254, 2021). "Downregulation of CDKN1A was noted in several cancers including lung cancer but upregulation of CDKN1A by various anticancer agents was reported to inhibit cell proliferation." (PMID 34299042, 2021). "By downregulating DUXAP8 in lung cancer cells, it is not only possible to inhibit the proliferation of pancreatic cancer cells through silencing CDKN1A and KLF2, but also to induce their apoptosis." (PMID 34431643, 2021). "As a result, this CRNDE/PRC2/CDKN1A axis mechanistically contributes to radioresistance in lung cancer cells via modifying the G1-S transition and triggering apoptosis." (PMID 32122355, 2020). "In our study, we also show that GSE down-regulates miR-106b, which in turn up-regulates CDKN1A gene mRNA expression and its respective protein p21 production in our lung cancer models." (PMID 29643994, 2018). "In A549 lung cancer cells, we observed the upregulation of CDKN1A and BAX after re-expression of RASSF1A confirming its apoptotic functions." (PMID 29179447, 2017). "Even though the CDKN1A gene has a tumor suppressive function, it has been correlated with increased protein expression in some types of tumor, such as lung carcinoma, hepatocellular carcinoma and head and neck cancer." (PMID 20169278, 2009). "Additionally, euchromatic histone lysine methyltransferase 1(EHMT1) downregulation of CDKN1A expression plays a crucial role in lung cancer proliferation, indicating the potential for further research on EHMT1 in lung cancer drug resistance." (PMID 38525426, 2024). "We determined whether CDKN1A gene expression influences the prognosis of lung cancer patients using a clinical database." (PMID 36054146, 2022). "However, lung cancer patients or squamous cell carcinoma patients with high CDKN1A expression showed better progression‐free survival compared to those with low CDKN1A expression." (PMID 36054146, 2022). "We finally investigated whether a difference in CDKN1A expression had any influence on the prognosis of lung cancer patients." (PMID 36054146, 2022). "Thus, we suggest that downregulation of CDKN1A expression by epigenetic regulation of EHMT1 plays an important role in lung cancer proliferation." (PMID 34214254, 2021). "In addition, CDKN1A, cyclin-dependent kinase inhibitor 1A (CDKN1A/p21), was found to be oncogenic in lung cancer by promoting anti-apoptosis and cell proliferation." (PMID 35096011, 2021). "In lung cancer, knockdown of UBE2M can promote the expression of cyclin-dependent kinase inhibitor 1 (CDKN1A and CDKN1B) and cyclin-associated proteins (such as G2/mitotic-specific cyclin-B1, Cyclin-A2, G1/S-specific cyclin-D3, and Cyclin-dependent kinase 4 homolog) in cell cycle progression." (PMID 33827629, 2021). "This has been confirmed particularly in patients with lung cancer, in which high expression levels of CDKN1A with wild-type EGFR status was associated with better survival, whereas CDKN1A expression with oncogenic EGFR mutations was correlated with poor outcome." (PMID 33430083, 2021). "Moreover, cell cycle analysis revealed that G1 arrest by EHMT1 knockdown was attenuated by CDKN1A knockdown in lung cancer cell lines." (PMID 34214254, 2021). "CDKN1A is a marker for lung cancer and uncontrolled cell proliferation." (PMID 28464886, 2017).
lung carcinoma (continued). "Indeed, we demonstrated the IRF9-dependent regulation of VCAN for the first time and showed that CDKN1A might be involved in lung cancer development and progression." (PMID 33430083, 2021). "In this study, we obtained eight lung cancer-related genes (CDC25C, TWIST1, HIF1A, DNMT1, PARP1, CDKN1A, CCNB1, and BIRC5) as seed nodes, using an RWR algorithm analysis to prioritize lung cancer related genes." (PMID 33193600, 2020). "MiR-106b transfection mimics the rearrangements of CDKN1A mRNA and p21, abolishing GSE-induced antiproliferative and anti-invasive properties in lung cancer cells." (PMID 33202575, 2020). "We created a score combining the expression of CDKN1A, ITGA6, and SNAI1, which was an independent prognostic biomarker for lung cancer patients." (PMID 31506430, 2019). "Among them, four genes involved in the GADD45 signaling pathway (CCNE2, CCND3, CDKN1A, and CCNB1), were reactivated by promoter DNA methylation in the GA-treated lung cancer H1299 cells." (PMID 29416619, 2018). "It has been reported that in lung carcinoma cells, TSPYL5 was able to suppress CDKN1A by modulating PTEN/AKT pathway." (PMID 28235398, 2017). "Increased ID2 protein levels in lung cancer cells did not further alter CDKN1A transcriptional activity." (PMID 37497010, 2023). "Additionally, we evaluated the expression of ALKBH5 target mRNAs CDKN1A and TIMP3 in lung cancer using the TCGA dataset." (PMID 35318440, 2022). "Upon NUPR1 depletion, proteins such as CDKN2A, CDKN1A, and CDKN1B, which directly regulate cell cycle progression, are involved in the NUPR1-mediated autolysosomal process, which is consistent with our previous observation in lung cancer cells." (PMID 33542201, 2021). "In this study, we found that EHMT1 is overexpressed in lung cancer and that EHMT1 modulates CDKN1A gene expression through the regulation of chromatin functions, subsequently promoting the proliferation of cancer cells by allowing them to evade apoptosis and cell cycle arrest." (PMID 34214254, 2021). "However, in contrast to lung carcinoma cells LNCaP cells lack PTEN, so any involvement of TSPYL5 in modulating CDKN1A must work by a PTEN-independent mechanism." (PMID 28235398, 2017). "Moreover, qPCR analysis revealed that overexpression of SLC16A4 upregulated the expression levels of CDKN1A and CDKN2A in A549 and H1299 cells, suggesting that SLC16A4 may suppress lung cancer cell proliferation by regulating the cell cycle." (PMID 40867526, 2025). "Besides, NT157 decreased expression of oncogenes BCL2, CCND1, MYB, and MYC and increased genes related to cellular stress and apoptosis, JUN, BBC3, CDKN1A, CDKN1B, FOS, and EGR1 (p < 0.05), favoring a tumor-suppressive cell signaling network in the context of lung cancer." (PMID 36224313, 2022). "Thus, we established the hypothesis that induction of CDKN1A expression by EHMT1 knockdown induces cell cycle arrest and apoptosis in lung cancer cells." (PMID 34214254, 2021). "In lung cancer, the lncRNA colorectal neoplasia differentially expressed (CRNDE) can bind with polycomb-repressive complex 2 (PRC2) and then recruit its key part EZH2 to p21 (cyclin-dependent kinase inhibitor 1A/CDKN1A) promoter regions and inhibit its transcription." (PMID 32122355, 2020).
lung carcinoma (continued). "Similar over-expression of FHIT in the same -/- kidney cells did not result in re-expression of p21 protein though it has been reported that Fhit overexpression induces expression of Cdkn1a mRNA in H460 lung cancer cells that are negative for endogenous Fhit protein expression." (PMID 24244712, 2013).
colon carcinoma (69 papers, 2007 to 2025). "To elucidate the potential of M1 virus personalized therapy by detecting CDKN1A deficiency, we compared the expression of CDKN1A in both tumor and adjacent non‐neoplastic tissue specimens from 38 colon cancer patients in the TCGA database." (PMID 33037696, 2020). "Consistently, our data prove that CDKN1A expression is consistently deficient in colon cancer, further supporting the reports that CDKN1A is a tumor suppressor." (PMID 33037696, 2020). "We compared the effects of CGGBP1 siRNA in HCT116 human colon cancer cell lines either WT or deficient for CDKN1A." (PMID 21733196, 2011). "For example, we identified in the HMF breast metastasis series significantly recurrent mutations of CDKN1A (known driver in bladder cancer), MAX (known in paragangliomas, endometrioid and colon carcinomas) and CDK12 (known in ovarian cancer)." (PMID 36937541, 2023). "The inhibition of FASN has previously been shown to induce the increased expression of CDKN1A in human colon carcinoma cells." (PMID 36139650, 2022). "SPUD generated by UV-induced intron-APA in CDKN1A was first described in colon carcinoma RKO cells." (PMID 37870464, 2023). "Additionally, the most recent efforts directed toward the CDKN1A gene have demonstrated that downregulation of this gene leads to colon cancer progression, and similar results have been reported for MAPK10." (PMID 28178311, 2017). "We observed that MAPK10 and CDKN1A were only altered in colon cancer (shown in cyan)." (PMID 28178311, 2017). "CDKN1A is a cyclin-dependent kinase inhibitor that plays a key role in regulating the cell cycle, especially the G1/S checkpoint, and its expression is lost in most cases of colon cancer." (PMID 26101583, 2015). "Previously, it was shown in colon cancer cells, downregulation of CCAT1 upregulated the expression of cyclin-dependent kinase inhibitor 1 A (CDKN1A) mRNA." (PMID 40781182, 2025). "TCF3 upregulation is caused by promoter hypomethylation during development, colon cancer progression, and the transcriptional upregulation of multiple cyclin-dependent kinase inhibitors like CDKN1A, p15INK4B, and p16INK4B, and probably CDKN3 in colon cancer." (PMID 39228892, 2024). "Previously, we described a strong activation of intron-APA sites after UV-treatment in colon carcinoma RKO cells, resulting in widespread expression of truncated transcripts, including from CDKN1A gene." (PMID 37870464, 2023). "In the human colon cancer CaCo-2 cell line, p-CA up-regulates the CDK inhibitor 1 (CDKN1A) expression and down-regulates other cell cycle-promoting proteins, resulting in the cell cycle arrest at the G2/M phase." (PMID 36672704, 2023). "To clarify the mechanism of pterostilbene activity against colon cancer cells, we also evaluated changes in the expression of the cell cycle regulatory genes CCND1 and CDKN1A." (PMID 36674631, 2023).
colon carcinoma (continued). "miR-6734 upregulates p21cip1/waf1 expression through modifying histones in the CDKN1A promoter and induces cell cycle arrest in colon cancer cells." (PMID 31514410, 2019). "Peroxisome proliferator activated receptor alpha (PPARα), a nuclear receptor that regulates lipid homeostasis, inhibits DNA methyltransferase 1 (DNMT1)-mediated cyclin dependent kinase inhibitor 1A (CDKN1A) and PRMT6-mediated cyclin dependent kinase inhibitor 1b (CDKN1B) to promote colon cancer." (PMID 35004688, 2021). "We could not confirm NBPF1-dependent CDKN1A upregulation in DLD1Tr21/NBPF1 colon cancer cells." (PMID 25958384, 2015).
hepatocellular carcinoma (67 papers, 2009 to 2026). A malignant tumor that arises from hepatocytes. "In this regard Ilangumaran and co-workers exhibited that hepatocellular carcinoma advances in SOCS1 deficiency through SOCS3-Dependent CDKN1A induction and NRF2 activation." (PMID 39286246, 2024). "In another study, downregulation of the G1 inhibitor CDKN1A in hepatocellular carcinoma was linked to upregulation of miR-519d." (PMID 29967761, 2018). "However, many tumors, including primary hepatocellular carcinoma show elevated CDKN1A expression, which is associated with high malignancy and poor prognosis." (PMID 41457818, 2026). "Previous research showed that CA significantly decreased the expression of the Cdkn2a and Cdkn1a genes in human dermal fibroblasts and human hepatoma cells." (PMID 40822955, 2025). "Study found that the expression of GHR and CDKN1A, one of the key inhibitors of cell cycle, were significantly down-regulated in hepatocellular carcinoma." (PMID 37322434, 2023). "SOCS1 deficiency, which increases susceptibility to hepatocellular carcinoma (HCC), promotes CDKN1A expression in the liver." (PMID 36765862, 2023). "CCND1, CDK4, MAPK1, CDKN1A, and E2F2 genes are linked to the development of hepatocellular carcinoma." (PMID 33959508, 2021). "Curcumin inhibited cell proliferation in hepatocellular carcinoma cells through upregulation of CDKN1A." (PMID 34299042, 2021). "In the case of hepatocellular carcinoma, reduced expression of CDKN1A and CDKN2B is connected with the EMT process, migration, and cell cycle progression." (PMID 34944712, 2021). "In order to gain molecular insight into the role of TRIM71 as an mRNA repressor, the present work focuses on the regulation of the known TRIM71 mRNA target CDKN1A, and its involvement in hepatocellular carcinoma cell proliferation." (PMID 31732746, 2019). "For example, miR-93 activated c-Met/PI3K (phosphoinosmde-3-kinase)/Akt pathway activity via inhibition of PTEN (phosphatase and tensin homolog deleted on chromosome ten) and CDKN1A (cyclin-dependent kinase inhibitor 1A) in hepatocellular carcinoma." (PMID 26919096, 2016). "After metformin treatment, the expression of CDKN1A is upregulated in hepatocellular carcinoma and bladder cancer cells." (PMID 26083494, 2015). "For example, MiR-519d had oncogenic roles in hepatocellular carcinoma and it targeted CDKN1A/p21, PTEN and TIMP2, which had important roles in atherosclerosis." (PMID 25333956, 2014). "Different types of neoplasms correlate with CDKN1A abnormalities, including cervical neoplasms, colorectal carcinoma, ovary carcinoma, bladder cancer, prostate cancer, hepatomas and others." (PMID 20169278, 2009). "Moreover, the expression of CDKN1A (also known as P21) is upregulated in hepatocellular carcinoma and bladder cancer cells after metformin treatment." (PMID 26083494, 2015). "For instance, hepatocellular carcinoma (HCC) frequently exhibits 2 to 10 fold amplification of oncogenes such as Cyclin D1, CDKN1A, KRAS, and MDM2." (PMID 41515655, 2026). "Almost half of these genes (purple-colored genes) were enriched in Hepatitis B, Hepatitis C and Hepatocellular carcinoma pathways including MYC, CD81, CDKN1A, IGF1R and so on which were reported in Hepatocellular carcinoma." (PMID 37051592, 2023). "Collectively, these results revealed that miR-93-5p inhibited PPARGC1A and CDKN1A genes, thereby decreasing the expressions of transcription factors CEBPB and promoting hepatoma cells proliferation." (PMID 29361788, 2018). "Both HNF4α and c-Myc proteins compete for control of the P21/CDKN1A gene transcription, and deletion of HNF4A in hepatocellular carcinoma cells results in significant up-regulation of c-Myc and enhanced cell proliferation rates." (PMID 25050814, 2014).
hepatocellular carcinoma (continued). "Another study revealed that tRF-3023 directly targets the mRNA of the cell cycle suppressor Cyclin-dependent kinase inhibitor 1A (CDKN1A, p21), accelerating the transition from G1 to S phase and thereby promoting malignant proliferation in hepatocellular carcinoma cells." (PMID 41550494, 2026). "Furthermore, MAPK1, E2F2, CDK4, CDKN1A, CCND1 were found key target genes of hepatocellular carcinoma pathway." (PMID 33959508, 2021). "In order to evaluate whether CDKN1A mRNA was similarly regulated in hepatocellular carcinoma cells, we knocked down UPF1 in HepG2 cells and found upregulated p21 protein levels and CDKN1A mRNA levels." (PMID 31732746, 2019). "However, later studies implicated that miR-519d also targeted several tumor suppressors, including CDKN1A/p21, PTEN and TIMP2, and thus potentially exerted oncogenic property in hepatocellular carcinoma development." (PMID 27006642, 2016). "In contrast, as a target gene relevant to execution and completion of apoptosis, the overexpressed CDKN1A triggered by HBx-induced HDAC4 inhibition was concordant with the earlier research that HBx can relieve a block on CDKN1A expression and prolong G1→S transition in human hepatoma cells." (PMID 32878239, 2020).